INS (insulin)
Diseases named in the same sentence as INS in open-access papers (continued):
Sharing a sentence is not in itself a finding about the gene and the disease.
cardiovascular disease (continued). "Funding statement (financial disclosure): The Relationship between Insulin Sensitivity and Cardiovascular disease (RISC) study was partly supported by EU Framework Program V grant QLG1-CT-2001-01252 with additional funding from AstraZeneca (Sweden)." (PMID 28846711, 2017). "Around 95% of the patients also used another insulin, and 24.2–24.7% had a history of cardiovascular disease (CVD)." (PMID 28702259, 2017). "While the scientific literature is emerging, several studies support hummus/chickpea consumption in relation to weight control, glucose, and insulin response, cardiovascular disease, cancer, and/or GI health." (PMID 27916819, 2016). "In adults, men have more visceral fat accumulation and lower plasma adiponectin, which contribute to gender differences in insulin sensitivity and vulnerability to cardiovascular disease." (PMID 27070153, 2016). "We identified several important pathways for cardiovascular disease, such as insulin, IGF1 and glucose signaling pathways, TGF-β pathway, as well as hypoxic and oxygen homeostasis regulation of HIF-1-α (and for a complete list)." (PMID 27317124, 2016). "Cardiovascular disease is a major cause of mortality in T2DM patients, and insulin or sulphonylureas effectively reduces the risk for microvascular complications, but not macrovascular events." (PMID 27881129, 2016). "As recent data suggest a detrimental role of exogenous insulin on cardiovascular disease, we also included a group of insulin users." (PMID 27887576, 2016). "In comparison to some previous trials that have excluded people with cardiovascular disease and insulin therapy, overall our cohort is more representative of the general population of older adults with T2D." (PMID 26554457, 2015). "Collectively, although it is clear that statins have beneficial effects on cardiovascular disease prevention, our study supports the evidence that long-term use of large doses of statins has adverse effects on glucose metabolism and insulin sensitivity." (PMID 24995341, 2014). "For example, lipoproteins and markers of inflammation have been used as surrogates for cardiovascular disease, insulin sensitivity for diabetes, and DNA damage for cancer." (PMID 24881334, 2013). "Although the exact mechanisms involved in these cardio-protective effects still are under investigation, the putative benefits on cardiovascular disease likely are the result of alcohol’s effects on lipids and insulin sensitivity." (PMID 24881334, 2013). "Clinically the use of angiotensin converting enzyme inhibitors and angiotensin receptor blockers has been shown to reduce cardiovascular disease and increase insulin sensitivity, suggesting a role for Ang II in the insulin resistance of the vasculature." (PMID 24276258, 2013). "Compared to non-diabetic people our monitoring showed declining excess mortality in non-insulin treated diabetic people mainly due to a decrease in mortality from cardiovascular diseases." (PMID 23837500, 2013). "PPARγ has many activities, leading to complicated and even paradoxical effects on adipocyte biology, insulin action, cardiovascular disease, inflammation." (PMID 22919315, 2012). "Our second aim was to compare fasting glucose, fasting insulin and HOMA-IR in strength of association with incident cardiovascular disease." (PMID 23300589, 2012). "The objective of this study is to compare fasting glucose, fasting insulin concentrations and HOMA-IR in strength of association with incident cardiovascular disease." (PMID 23300589, 2012). "To enable a comparison between cardiovascular disease risks for glucose, insulin and HOMA-IR, we calculated pooled relative risks per increase of one standard deviation." (PMID 23300589, 2012). "A number of previous meta-analyses have investigated the association between fasting glucose, fasting insulin or HOMA-IR concentrations and cardiovascular disease by comparing high to low concentrations." (PMID 23300589, 2012).
cardiovascular disease (continued). "Cohort studies or nested case-control studies that investigated the association between fasting glucose, fasting insulin or HOMA-IR and incident cardiovascular disease, were eligible." (PMID 23300589, 2012). "Overall former HT users had a significantly worse cardiovascular disease risk profile than current HT users: higher total cholesterol, higher LDL cholesterol, higher glucose and insulin, and lower HDL cholesterol." (PMID 22957258, 2012). "Our pooled relative risks of cardiovascular disease (glucose: 1.44, insulin: 1.28, HOMA-IR: 1.44) are within the range of pooled relative risks reported in previous meta-analyses." (PMID 23300589, 2012). "Given that this patient group had cardiovascular disease and a relatively high fasting glucose (6.0 [±1.0] mmol/L) it is likely that these patients were insulin resistant with hyperinsulinaemia." (PMID 19828038, 2009). "A Paleolithic diet thus conferred higher insulin sensitivity, which is central to the prevention of cardiovascular disorders, and consistent with our finding in humans." (PMID 17081292, 2006). "Calcium exerts its influence on the susceptibility to cardiovascular disease (CVD) via a variety of pathways, encompassing modulation of serum cholesterol levels, insulin release, and insulin sensitivity, as well as impacting vasodilation, adiposity, and vascular calcification." (PMID 40761350, 2025). "As an insulin‐sensitising agent, metformin improves insulin sensitivity and glucose uptake in T2DM while also being recognised as a recommended adjunct therapy in overweight T1DM patients, potentially reducing cardiovascular disease (CVD) risk." (PMID 40512873, 2025). "Mechanistically, insulin can contribute to fluid retention and weight gain, and it has been shown that insulin therapy in T2DM patients is associated with an increased prevalence of HF and cardiovascular disease mortality." (PMID 41001676, 2025). "Furthermore, HDL-C possesses anti-inflammatory and antioxidant properties and improves insulin sensitivity, all of which contribute to the prevention of metabolic and cardiovascular diseases." (PMID 39773780, 2025). "Furthermore, phenolic compounds are known to enhance insulin sensitivity, reduce blood glucose levels, and protect against complications such as DN, retinopathy, and cardiovascular disease." (PMID 41150789, 2025). "The reason why 2hPG is more predictive of cardiovascular disease may be related to its stronger indication of postprandial glucose metabolism and insulin resistance." (PMID 40954930, 2025). "However, further studies are needed to investigate the relationship between insulin and cardiovascular disease." (PMID 38184598, 2024). "However, several factors related to cardiovascular disease were improved, such as insulin sensitivity of adipose tissue, high sensitivity C-reactive protein (hs-CRP) and oxidized low-density lipoprotein cholesterol (LDL-C)." (PMID 38519764, 2024). "The triglyceride glucose (TyG) index is a new and low-cost marker to determine insulin resistant which may be a predictor of cardiovascular disease (CVD)." (PMID 38347581, 2024). "The outcome measurements were cardiometabolic indices and risk factors for metabolic and cardiovascular diseases, including anthropometric index (body weight, BMI, WC), BP, lipid profile (TG, TC, HDL, LDL), glycemic markers (FBG, Hb1AC, Insulin), and inflammatory markers (CRP, IL-6, TNF-α)." (PMID 39285289, 2024). "Consistent results were found in subgroup analyses stratified by eGFR; HbA1c; presence of cardiovascular disease, proteinuria, or diabetic complications; use of metformin, insulin, SGLT2is, ACEis, or ARBs; previous GLP-1 RA treatment; potential indications; LDL cholesterol level; and BMI." (PMID 39133485, 2024).
cardiovascular disease (continued). "Partial replacement of saturated fatty acid (SFA) with n-6 polyunsaturated fatty acid (PUFA) improves blood lipid profile, decreases the risk of cardiovascular disease (CVD), improves glucose-insulin homeostasis and may decrease the risk of total mortality." (PMID 38327998, 2024). "Throughout this paper, we discussed the discovery and physiological function of mitochondrial-derived polypeptide MOTS-c, and the application of MOTS-c in the treatment of various diseases, such as aging, cardiovascular disease, insulin resistance, and inflammation." (PMID 36761202, 2023). "The inhibition of this signaling cascade impedes the glucose transport to the interior of the cells of insulin-dependent tissues (such as adipose, muscle and liver tissue), contributing to IR and subsequently to the development of T2D and cardiovascular diseases." (PMID 36771304, 2023). "In the Relationship between Insulin Sensitivity and Cardiovascular Disease (RISC) study, individuals with insulin hypersecretion tended to be older, had higher percent fat mass, worse lipid profile and higher liver insulin resistance indices compared with the rest of the cohort." (PMID 37200851, 2023). "We measured 828 proteins in the fasting plasma of 966 participants from the Relationship between Insulin Sensitivity and Cardiovascular disease (RISC) study and 745 participants from the Uppsala Longitudinal Study of Adult Men (ULSAM) using a high-throughput proximity extension assay." (PMID 37329449, 2023). "Thus, the inflammatory mechanisms of insulin resistance impact vascular endothelium and metabolic targets of insulin similarly, contributing to both metabolic and cardiovascular diseases." (PMID 38203642, 2023). "Considering that diabetes contributes to the development of various cardiovascular diseases, regulation of insulin sensitivity may be one of the most relevant functions of WAT in terms of the risk for cardiovascular disease." (PMID 37106699, 2023). "However, every effort should be made to include dynamic measures of glucose control and insulin sensitivity as secondary outcomes where possible given the strong link with cardiovascular disease and mortality in individuals with T2DM." (PMID 37072802, 2023). "Changes in insulin sensitivity, inflammatory factors, and oxidative stress in sarcopenic patients may play a role in the development of cardiovascular disease." (PMID 37370012, 2023). "Chemerin is a novel player that might contribute to a wide variety of cardiovascular diseases, amongst others, by stimulating adipogenesis, inflammation and contraction, and by influencing thermogenesis, steroidogenesis and insulin signaling." (PMID 37447205, 2023). "The results imply that adiponectin levels and cardiovascular disease risk are not influenced by blood glucose and lipid status, suggesting that adiponectin directly protects blood vessels rather than through insulin sensitivity and diabetes." (PMID 37822930, 2023). "Together, these results suggest that impaired insulin signaling is an important trigger of neurodegeneration among females and may explain the greater prevalence of comorbidities, including cardiovascular disease in females with AD." (PMID 36389068, 2022). "Interestingly, the CVD group exhibited improved lipid parameters and glycemic control, which was attributed to statins-use and insulin therapy after the occurrence of cardiovascular diseases." (PMID 35493201, 2022). "Unexpected, insulin treatment had neither a association with baseline D-dimer levels nor a association with cardiovascular diseases incidences in diabetic patients." (PMID 35246061, 2022). "It has been suggested that the link between WBC count and cardiovascular disease may be represented by a decrease in insulin sensitivity." (PMID 35252251, 2022). "The DASH diet has been shown to reduce blood pressure, a lower risk of cardiovascular disease, improve insulin sensitivity, and aid in weight loss in non-pregnant populations." (PMID 35495932, 2022).
cardiovascular disease (continued). "Mineralocorticoid receptor antagonists can not only lower blood pressure, but also improve insulin sensitivity, relieve oxidative stress and reduce the inflammatory response of MetS, which could eventually prevent the occurrence of cardiovascular disease." (PMID 34513942, 2021). "This study analysed the association between different insulin resistance indices and vascular ageing and arterial stiffness measurements using cfPWV and baPWV in an adult Caucasian population without cardiovascular disease." (PMID 34945044, 2021). "An extensive review of randomized controlled trials demonstrated that dietary MUFA (20–25% of the total energy) prevented or ameliorated cardiovascular disease by modulating several biological parameters, such as the lipids profile, blood pressure, and insulin sensitivity." (PMID 33800396, 2021). "It is well known that regular physical activity and exercise, particularly endurance exercise, were proven to enhance cardiovascular functions, insulin sensitivity, thereby decreasing the prevalence of cardiovascular diseases and the mortality from related complications during advancing aging." (PMID 33573269, 2021). "Moreover, fasting insulin levels should be also evaluated at least in a similar fashion in comparison to BMI from a clinical perspective for preventing cardiovascular diseases." (PMID 34746266, 2021). "In addition, multi-LAB mixture showed its potential for preventing cardiovascular diseases and increasing insulin sensitivity by increasing stearic acid and oleic acid concentrations in serum." (PMID 32824501, 2020). "Our findings showed that oligopin failed to significantly influence cardiovascular disease risk factors (insulin, fasting glucose, lipid profiles and hs-CRP); this is an observation previously recorded in the case of overweight and obese adults." (PMID 33408691, 2020). "The therapeutic effect of PA on these patients has been proved to be related to a better control of glucidic and lipidic metabolism, also on blood pressure and cardiovascular diseases, as well as reduction of BMI and an increase of insulin sensitivity in skeletal muscle." (PMID 33467285, 2020). "Regular exercise training offers ample health benefits for persons living with T1D, resulting in improved cardiorespiratory fitness, improved vascular health, decreased insulin requirements, improved endothelial function, reduced cardiovascular disease risks, and better self-rated quality of life." (PMID 30781593, 2019). "Cardiovascular disease increasingly contributes to global morbidity and mortality, and the heart as an insulin-sensitive organ may become insulin resistant, which manifests as micro- and/or macrovascular complications due to diabetic complications." (PMID 29484207, 2018). "Some studies have shown that diets low in saturated fats and rich in fruits and vegetables reduce the risk of cardiovascular disease, while an increase in physical aerobic activity reduces insulin levels regardless of weight loss." (PMID 29402762, 2018). "Thus, this risk of maintaining the systemic inflammation and develop cardiovascular diseases, seems be more significant in women with COPD-BS than COPD-TS, especially since were C-peptide and insulin are higher in women with COPD-BS." (PMID 30514305, 2018). "Impaired insulin signaling could be central to the development of the MetS and can promote cardiovascular diseases through abnormal lipid metabolism." (PMID 28191276, 2017). "Adipose tissue metabolism, composite insulin sensitivity index (C-ISIMatsuda), and other cardiovascular disease risk biomarkers were not different between groups." (PMID 28753161, 2017). "Four randomized, parallel design human trials have reported that consumption of blueberries may beneficially affect insulin sensitivity and other early biomarkers of cardiovascular disease, such as blood pressure, endothelial function, and oxidative stress." (PMID 32153825, 2017).
cardiovascular disease (continued). "HOMA-IR incorporates both glucose and insulin concentrations and shows stronger association with cardiovascular disease than glucose or insulin concentration alone in non-diabetic patients." (PMID 28448601, 2017). "Emerging research suggests that chickpeas and hummus may play a beneficial role in weight management and glucose and insulin regulation, as well as have a positive impact on some markers of cardiovascular disease (CVD)." (PMID 27916819, 2016). "However, direct evidence of how HUA affects insulin resistance in cardiomyocytes and a pathological mechanism to explain the association of HUA and cardiovascular disease remains to be clarified." (PMID 26836389, 2016). "Furthermore, IL—6 is considered as a marker of the prognostic of resistance to insulin and cardiovascular diseases." (PMID 25875942, 2015). "Except a weak inverse association with fasting insulin in males, there was no clear association between serum vitamin D levels and cardiovascular disease risk factors in fully adjusted models." (PMID 26079685, 2015). "This study showed a difference in insulin regimen between insurance types, and HbA1c and several cardiovascular disease risk factors were no longer significant after insulin regimen was controlled for." (PMID 24955334, 2014). "In the present review we summarize the current knowledge about the influence of adiponectin on insulin sensitivity and endothelial function, discussing its forthcoming prospects and potential role as a manifold therapeutic target for MS, diabetes, and cardiovascular disease." (PMID 24957699, 2014). "The effect of insulin on the SHBG production is of particular interest as low SHBG levels can, in part, predict the development of T2D and are associated with increased risk of cardiovascular disease and death." (PMID 23781314, 2013). "Future trials may be required to determine the potential long-term clinical benefits of bolus insulin analogues in preventing cardiovascular diseases in diabetic patients." (PMID 24244557, 2013). "Management of the disease should attempt to modify different aspects of an individual’s life, such as eating habits, physical activity levels, correct use of multiple medications and insulin administration, laboratory monitoring, and screening for cardiovascular diseases." (PMID 23972112, 2013). "Additionally, much interest in various adipokines (e.g. resistin, leptin, adiponectin) has been generated due to their relationship to appetite, energy expenditure, insulin sensitivity and cardiovascular disease." (PMID 21092228, 2010). "Reducing the oxidative stress by CQ and/or IG [independently submitted for publication] could improve insulin sensitivity, inflammation, body-mass index, cardiovascular disease and related conditions." (PMID 18377661, 2008). "Therefore, the molecular pathways linking glucose autocorrelation to cardiovascular disease may share common mechanisms with those linking insulin clearance to cardiovascular disease." (PMID 41537426, 2026). "Despite GALNT16 being classified as an N‐acetylgalactosaminyltransferase, previous studies have implicated it in protein and lipid metabolism, as well as in AMPK, prolactin, and insulin/IGF signaling pathways, and it may also play a role in lipid metabolism associated with cardiovascular diseases." (PMID 41322030, 2025). "Biologically, adiponectin potentially plays a pivotal role in cardiovascular disease by improving insulin sensitivity and exerting anti-atherogenic and anti-inflammatory properties, that is, theoretically, elevated adiponectin could protect against cardiovascular disease." (PMID 37897683, 2024). "However, it should not be disregarded the probability that blood triglycerides’ may be increased to levels related to a higher likelihood of developing cardiovascular diseases in overweight and insulin-resistant individuals." (PMID 38921683, 2024).